MATN2 (matrilin 2)
Description:
Involved in matrix assembly.
Tractability: Antibody: UniProt places it where antibodies can reach, with medium confidence; UniProt predicts a signal peptide or a membrane-spanning region; its Gene Ontology location is reachable by antibodies, with medium confidence. PROTAC: its protein half-life has been measured.
Gene: Protein-coding gene on chromosome 8 (97,868,840 to 98,036,769, forward strand). Ensembl gene ENSG00000132561.
Subcellular location: Secreted
Gene Ontology:
Molecular function: protein binding; extracellular matrix structural constituent; calcium ion binding
Biological process: extracellular matrix organization
Cellular component: extracellular matrix; matrilin complex; non-collagenous component of basement membrane; non-collagenous component of interstitial matrix; extracellular region
Genetic constraint (gnomAD): Loss-of-function variants: 61 observed, 93.23 expected, observed/expected ratio (o/e) 0.65, 90% interval 0.53 to 0.81. The upper end of that interval is the gene's LOEUF score, 0.81, which puts it in group 3 of 6, group 1 being the genes least tolerant of losing a copy. Missense variants: 978 observed, 1,204.1 expected, observed/expected ratio (o/e) 0.81, 90% interval 0.77 to 0.86. Synonymous variants: 420 observed, 458.23 expected, observed/expected ratio (o/e) 0.92, 90% interval 0.85 to 0.99.
Homologues: Orthologues: chimpanzee MATN2 (99% identical), macaque MATN2 (94% identical), pig MATN2 (92% identical), rabbit MATN2 (88% identical), mouse Matn2 (87% identical), dog MATN2 (85% identical), guinea pig MATN2 (84% identical), rat Matn2 (84% identical), tropical clawed frog matn2 (55% identical). Paralogues in human: MATN4 (30% identical), MATN1 (26% identical), MATN3 (20% identical), COL12A1 (19% identical), COL14A1 (19% identical), COL6A6 (19% identical), COL6A3 (18% identical), COL6A5 (17% identical), VWA2 (16% identical), COCH (13% identical), VIT (8% identical), VWA1 (8% identical).
Diseases named in the same sentence as MATN2 in open-access papers:
MATN2 is named in the same sentence as 39 diseases in open-access papers, as found by Europe PMC text mining. Sharing a sentence is not in itself a finding about the gene and the disease. The quoted sentences say what the papers report.
thyroid cancer (5 papers, 2022 to 2025). "In addition, matrilin-2 expression can improve the diagnosis of cytologically indeterminate thyroid cancers." (PMID 40265010, 2025). "For instance, Matrilin 2 (MATN2) and Rap1-GTPase activating protein 1 (RAP1GA1) were notably underexpressed in thyroid carcinoma samples." (PMID 40346322, 2025).
breast carcinoma (4 papers, 2011 to 2025). "A potential further work would be to investigate the relationship between MATN2 and breast cancer, since it has been revealed to have a strong functional relationship with a well-established breast cancer biomarker." (PMID 40004168, 2025). "The relationship between MATN2 and breast cancer is currently unclear; MATN2 is a protein-coding gene that is speculated to be involved in the formation of filamentous networks in the extracellular matrices of several tissues." (PMID 40004168, 2025). "MATN2 and SCGB2A2 are upregulated in ovarian cancer; S100P is upregulated in prostate cancer, invasive ductal carcinomas, and pancreatic cancer; LDHB is a biomarker for triple negative breast cancer; and TNC is associated with Tamoxifen resistance in breast cancer." (PMID 27449296, 2016).
hepatocellular carcinoma (3 papers, 2014 to 2024). A malignant tumor that arises from hepatocytes. "For example, Expression of matrilin-2 was up-regulated in hepatocellular carcinoma and Sporadic pilocytic astrocytoma." (PMID 38889378, 2024). "MATN2 is an extracellular matrix protein involved in the formation of filamentous networks; its expression is increased in hepatocellular carcinoma and liver cirrhosis." (PMID 38003580, 2023). "While in normal human liver MATN2 is located in the walls of portal vessels, in hepatocellular carcinoma (HCC) it is intensively detected in the tumor vessels." (PMID 24691449, 2014).
osteoarthritis (3 papers, 2014 to 2020). A noninflammatory degenerative joint disease occurring chiefly in older persons, characterized by degeneration of the articular cartilage, hypertrophy of bone at the margins and changes in the synovial membrane. "The expression level of matrilin-2 was remarkably increased in the tissues of osteoarthritis developmental articular cartilage, compared to normal healthy tissues." (PMID 24741569, 2014). "The observation demonstrates that the expression of matrilin-2 may be used as a potential biomarker of osteoarthritis in articular cartilage." (PMID 24741569, 2014). "The gene with the lowest P value in our EWAS, MATN2 plays a critical role in the differentiation and maintenance of skeletal muscles, peripheral nerves, liver and skin during development and regeneration and is suggested as a potential biomarker in the early stage of osteoarthritis." (PMID 32114984, 2020). "Matrilin-2 may play an important role in the communication of matrix to matrix and matrix to cells and will be used as a potential biomarker in the early stage of osteoarthritis of articular cartilage." (PMID 24741569, 2014). "Previously, we had not observed age-associated osteoarthritis in single MATN1, MATN2, MATN3, or double MATN1/MATN3 deficient mice." (PMID 31963938, 2020).
corneal stromal dystrophies (2 papers, 2012 to 2022). "Previously we demonstrated elevated matrilin-2 levels in the corneal epithelium and stroma in different corneal stromal dystrophies." (PMID 36294311, 2022). "Immunolocalization of fibrillin-2, matrilin-2, matrilin-4, and tenascin-C in normal and stromal dystrophy corneas (maximum and minimum gray levels are 0 and 255, respectively)." (PMID 22876117, 2012). "The present study investigated the expression patterns of fibrillin-2, tenascin-C, matrilin-2, and matrilin-4 in granular and lattice type I corneal stromal dystrophy samples." (PMID 22876117, 2012).
COVID-19 (2 papers, 2023). A disease caused by infection with severe acute respiratory syndrome coronavirus 2. "Importantly, several unreported elevated proteins in patients with COVID-19, such as RBP2 and BST2, which show anti-microbial activity, along with proteins involved in extracellular matrix remodeling, including MATN2 and COL6A3, were identified." (PMID 37047248, 2023).
neuroblastoma (2 papers, 2013 to 2025). Neuroblastoma (NB) is the most common solid, extracranial childhood tumor. "Downregulation of tumor suppressor genes PMP22 and MATN2 is associated with high-risk neuroblastoma tumors." (PMID 41189817, 2025). "MATN2 and glial differentiation marker PMP22 are among the upregulated genes induced by GLI family zinc finger 1 (GLI1) in SH-SY5Y neuroblastoma cells." (PMID 41189817, 2025). "To determine the functional significance of AKT2-mediated inhibition of Gli1 transcriptional activity in neuroblastoma, we quantified the mRNA levels of RET and MATN2 as downstream targets of Gli1 with or without AKT2 overexpression." (PMID 23900341, 2013).
Anxiety (1 paper, 2024). Intense feelings of nervousness, tension, or panic often arise in response to interpersonal stresses. "Proteins associated with the anxiety/depression (IL-1R2 P = 0.11 and MATN2 P = 0.61) and cognitive groups (CTSO P = 0.64 and NFASC P = 0.41) were not different between men and women in either age group, consistent with the absent/weak association between sex and these outcomes identified by PLR." (PMID 38589621, 2024). "IL-1R2, MATN2 and COLEC12 were associated with cardiorespiratory symptoms, fatigue and anxiety/depression; MATN2, CSF3 and C1QA were elevated in gastrointestinal symptoms and C1QA was elevated in cognitive impairment." (PMID 38589621, 2024). "COLEC12 and markers of endothelial and mucosal inflammation (MATN2, PCDH1, ROBO1, ISM1, ANGPTL2, TGF-α and TFF2) were highly correlated within the cardioresp, fatigue and anxiety/depression groups." (PMID 38589621, 2024).
atherosclerosis (1 paper, 2018). A disease characterized by the build-up of fatty material and calcium deposition in the arterial wall resulting in partial or complete occlusion of the arterial lumen. "Among novel factors in atherosclerosis, we identified matrilin-2, the collagen IV crosslinking enzyme peroxidasin as well as the poorly characterized MAM-domain containing 2 (Mamdc2) protein as being up-regulated in the ECM during atherogenesis." (PMID 29208753, 2018).
calcific aortic valve disease (1 paper, 2024). "In terms of inflammation, one study showed that soluble MATN2 promotes inflammatory activity via activation of the TLR/PKR/NFKB signalling pathway in calcific aortic valve disease." (PMID 38235996, 2024).
Fuchs endothelial corneal dystrophy (1 paper, 2022). Fuchs endothelial corneal dystrophy (FECD) is the most frequent form of posterior corneal dystrophy (see this term) and is characterized by excrescences on a thickened Descemet membrane (corneal guttae), generalized corneal edema, with gradually decreased visual acuity. "In summary, the present study investigated the immunohistochemical expression pattern of tenascin-C, matrilin-2, and aggrecan in advanced forms of corneal endothelial pathology such as pseudophakic bullous keratopathy and Fuchs’ endothelial corneal dystrophy." (PMID 36294311, 2022). "The aim of this study was to examine the expression of tenascin-C, matrilin-2, and aggrecan in irreversible corneal endothelial pathology such as pseudophakic bullous keratopathy (PBK) and Fuchs’ endothelial corneal dystrophy (FECD), which most frequently require corneal transplantation." (PMID 36294311, 2022).
glaucoma (1 paper, 2024). Increased pressure in the eyeball due to obstruction of the outflow of aqueous humor. "The function of MATN2 in the glaucoma is unclear, especially in inflammation, ECM formation and nerve growth." (PMID 38235996, 2024).
lattice type I corneal dystrophy (1 paper, 2012). "Fibrillin-2, tenascin-C, matrilin-2, and matrilin-4 may be characteristic of the pathogenesis of either the granular or lattice type I corneal dystrophy, as revealed by immunohistochemical analysis." (PMID 22876117, 2012). "Fibrillin-2, tenascin-C, matrilin-2, and matrilin-4 may be markers of the pathogenesis of either granular or lattice type I corneal dystrophy, as revealed by immunohistochemical analysis." (PMID 22876117, 2012).
liver cancer (1 paper, 2022). An epithelial or non-epithelial malignant neoplasm that arises from the liver. "We found that expression of the Neanderthal MATN2 allele was significantly lower than the modern human allele in liver cancer compared to unaffected livers." (PMID 36503519, 2022). "Consistent with this, we observed higher expression of MATN2 in liver cancer patients with Neanderthal introgression compared to liver cancer patients without Neanderthal introgression." (PMID 36503519, 2022).
lung carcinoma (1 paper, 2021). "In keeping with the fact that lung cancer cells have more complex genetic landscapes than SCCOHT15,62, only four genes, namely ITPR3, MATN2, EHD4, and ATP2B4, were consistently upregulated by SMARCA4 in both cancer types." (PMID 34518526, 2021).
metastatic tumours (1 paper, 2017). "Notably, CCT365623 and BAPN elicit a significant reduction in MATN2 protein levels in both the primary and metastatic lung tumours and this is accompanied by the loss of EGFR from the plasma membranes of the cells in both the primary and metastatic tumours." (PMID 28416796, 2017).
muscular dystrophy (1 paper, 2014). Muscular dystrophy (MD) refers to a group of more than 30 genetic diseases characterized by progressive weakness and degeneration of the skeletal muscles that control movement. "At late stages of regeneration, signs of mild muscular dystrophy were seen in Matn2−/− mice, including necrosis, inflammation and increased fibrosis." (PMID 24895400, 2014).
pilocytic astrocytoma (1 paper, 2017). Pilocytic astrocytoma is a rare subtype of low-grade glioma of the central nervous system characterized by a well circumscribed, often cystic, brain tumor with a discrete mural nodule and long, hair-like projections that extend from the neoplastic astrocytes. "Of note, the MATN2 protein is elevated in NF1-associated pilocytic astrocytoma with an unusually aggressive clinical phenotype; it will therefore be interesting to further examine the effects of MATN2 and potential regulation by miR-124 and miR-153 in SEPN." (PMID 29383182, 2017).
rheumatoid arthritis (1 paper, 2020). A chronic, systemic autoimmune disorder characterized by inflammation in the synovial membranes and articular surfaces. "The neoexpression of MATN1 was also observed in the cartilage of OA or rheumatoid arthritis patients, and MATN2 was recently observed in total knee arthroplasty and suggested as a biomarker for OA." (PMID 31963938, 2020).
thyroid tumor (1 paper, 2022). A benign or malignant neoplasm affecting the thyroid gland. "We also integrated differentially downregulated DEGs from the datasets and identified six downregulated DEGs, namely, MPPED2, TNFRSF11B, FHL1, CRABP1, MATN2, and TFF3, collectively known as thyroid tumor-downregulated genes (TTDGs)." (PMID 35990603, 2022).
tumor (11 papers, 2011 to 2025). "Molecular profiling of the tumor and ctDNA revealed a novel MATN2-RSPO RNA fusion and a novel NTRK3 mutation, respectively." (PMID 37626821, 2023). "In matrilin-2-deficient animals, however, significantly more, and more voluminous tumor foci have developed." (PMID 24691449, 2014). "Genes encoding components of the ECM, including TNXB and MATN2 were identified among downregulated transcripts, together with other participants in tumor progression, including growth factors, such as FIGF and growth factor receptors, such as TGFBR3." (PMID 21611158, 2011). "In Matn2-deficient livers we could demonstrate spontaneous appearance of tumorous foci, as well as markedly increased tumor formation upon diethylnitrosamine (DEN) treatment." (PMID 24691449, 2014). "This enhanced proliferative capacity was further increased in the tumor nodules of DEN-treated Matn2-/- livers." (PMID 24691449, 2014). "Our study suggests that Matn2 functions as a tumor suppressor in hepatocarcinogenesis, and in this process activation of EGFR together with that of Erk1/2, as well as inactivation of GSK-3β, play strategic roles." (PMID 24691449, 2014). "DEN treatment induced macroscopic tumors in 78% of WT mice, whereas tumor frequency was 100% in the liver of Matn2-/- animals." (PMID 24691449, 2014). "KGF also induced downregulation of a set of genes specifically upregulated in SCC cells compared to normal keratinocytes, including genes associated with tumor progression (MMP13, MATN2, CXCL10, and IGFBP3)." (PMID 22427941, 2012). "The function of matrilin-2 is highly variable in the human body, such as promotion of axonal growth and Schwann cell migration during peripheral nerve regeneration, modulation of dermal wound healing, tumor development, and muscle regeneration." (PMID 36294311, 2022). "This study provides evidence that Matn2 functions as a tumor suppressor in hepatocarcinogenesis." (PMID 24691449, 2014). "Matrilin-2 functions in early cell differentiation during embryonal development, promotes axonal growth and Schwann cell migration during peripheral nerve regeneration, modulates wound healing in the skin and plays a role in tumor development." (PMID 22876117, 2012). "Ultimately, akin to BAPN or LOX gene ablation, CCT365623 downregulates MATN2, impeding EGFR plasma membrane localization in tumors and inhibiting tumor growth and metastasis in mice." (PMID 39979279, 2025). "Although panomics revealed low RNA and protein expression of CA1, CLCA1, MATN2, AHCYL2, and FCGBP in malignant tissues compared to healthy colon mucosa, no differentially expressed RNA or protein targets were detected between tumour and metastatic tissues." (PMID 36691026, 2023). "MATN2 is localized downstream of several growth factor receptors, such as IGF-1R, GPER, and TGFβ1, and involved in tumor progression by stimulating the growth, chemotaxis, and migration of cancer cells." (PMID 35976950, 2022). "Critically, we observe significantly less staining of MATN2 and EGFR in the plasma membranes of the cells in the LOX-depleted tumours than in the cells of shRNA control tumours." (PMID 28416796, 2017). "However, no information is available about the consequences of Matn2 deficiency on tumor formation." (PMID 24691449, 2014). "However, it remains unknown how MATN2 contributes to tumor formation." (PMID 24691449, 2014). "Second, tumor subsets enriched for microenvironment features, including hypoxia markers (e.g., Slc2a1, Pdk1, Car9), extracellular matrix (ECM) genes (e.g., Matn2, Fn1, Dcn, Col6a1), vasculature (e.g., Cdh5, Pecam1, Vwf), and interferon response genes (e.g., Rsad2, Ifit3, Gbp3, Cxcl10, Cd274)." (PMID 40171265, 2025). "On the basis of our data, we propose a model whereby LOX activates the secreted protease HTRA1, which inhibits TGFβ1 signalling, causing increased expression of the EGF-like domain containing protein MATN2, which then enhances EGFR signalling to drive tumour growth and metastasis." (PMID 28416796, 2017).
tumor (continued). "MATN2 traps EGFR at the cell surface for enhanced activation by EGF, driving tumour progression." (PMID 28416796, 2017). "Finally, like BAPN or genetic ablation of LOX, CCT365623 downregulates MATN2 and inhibits EGFR plasma membrane localization in tumours, and it suppresses tumour growth and metastasis in mice." (PMID 28416796, 2017). "Focal Ki-67 positivity of these samples provided additional support to our presumption that the lack of Matn2 drives the liver into a pro-proliferatory state, making it prone to tumor development." (PMID 24691449, 2014). "In the liver of Matn2-/- mice, spontaneous microscopic tumor foci were detected without DEN treatment." (PMID 24691449, 2014). "Furthermore, quite surprisingly, sporadic microscopic tumor foci spontaneously appeared in the liver of Matn2-/- mice without DEN treatment at age of 10 months." (PMID 24691449, 2014). "Moreover, not only the number but also the size of tumors was significantly larger in the livers lacking Matn2, (mean tumor volumes, 248 mm3 vs. 43 mm3, p<0.01)." (PMID 24691449, 2014).
cancer (9 papers, 2012 to 2025). A tumor composed of atypical neoplastic, often pleomorphic cells that invade other tissues. "Matn2-/- animals showed increased susceptibility to cancer induction, and spontaneously developed atypical microscopic foci in the liver." (PMID 24691449, 2014). "MATN2 expression has been shown to be significantly altered during cancer progression." (PMID 36691026, 2023). "The identification of genes with high functional similarity to known biomarkers, such as MATN2 to COL10A1, opens new avenues for research into the roles of these genes in cancer progression." (PMID 40004168, 2025). "RT‐qPCR was utilized to detect the expression pattern of MATN2, FOXE1, and ITGA3 in PTC and papa‐cancer tissues." (PMID 30941771, 2019). "Activation of the MAPK pathway most likely was a critical event related to the absence of Matn2 from the ECM, and this might be one of the key alterations responsible for the increased susceptibility of hepatocytes to cancer development." (PMID 24691449, 2014). "No significant change was found in MATN2 expression between PTC and papa‐cancer tissues." (PMID 30941771, 2019).
genetic disease (1 paper, 2022). "The matrilin MATN2 is a poorly understood matrix protein that has not been linked to human genetic disease." (PMID 35584218, 2022).
MATN2 also shares sentences with these, for which no sentence is quoted: prostate carcinoma (2 papers); adenoma (1); breast tumors (1); Cognitive impairment (1); corneal dystrophies (1); depression (1); diabetes (1); invasive ductal carcinomas (1); lattice corneal dystrophy (1); liver cirrhosis (1); metabolic syndrome (1); neurodegenerative disease (1); Obesity (1); ovarian carcinoma (1); pancreatic cancer (1); triple-negative breast carcinoma (1).